IL36A (interleukin 36 alpha)
Description:
Cytokine that binds to and signals through the IL1RL2/IL-36R receptor which in turn activates NF-kappa-B and MAPK signaling pathways in target cells linked to a pro-inflammatory response. Part of the IL-36 signaling system that is thought to be present in epithelial barriers and to take part in local inflammatory response; similar to the IL-1 system with which it shares the coreceptor IL1RAP. Seems to be involved in skin inflammatory response by acting on keratinocytes, dendritic cells and indirectly on T-cells to drive tissue infiltration, cell maturation and cell proliferation. In cultured keratinocytes induces the expression of macrophage, T-cell, and neutrophil chemokines, such as CCL3, CCL4, CCL5, CCL2, CCL17, CCL22, CL20, CCL5, CCL2, CCL17, CCL22, CXCL8, CCL20 and CXCL1, and the production of pro-inflammatory cytokines such as TNF, IL-8 and IL-6. In cultured monocytes up-regulates expression of IL-1A, IL-1B and IL-6. In myeloid dendritic cells involved in cell maturation by up-regulating surface expression of CD83, CD86 and HLA-DR. In monocyte-derived dendritic cells facilitates dendritic cell maturation and drives T-cell proliferation. May play a role in pro-inflammatory effects in the lung.
Synonyms: IL-1F6; FIL1E; IL1F6; FIL1; IL1(EPSILON); MGC129553; MGC129552; FIL1(EPSILON)
Tractability: Antibody: UniProt places it where antibodies can reach, with high confidence; its Gene Ontology location is reachable by antibodies, with high confidence. PROTAC: ubiquitination databases record sites on it.
Gene: Protein-coding gene on chromosome 2 (113,005,459 to 113,008,044, forward strand). Ensembl gene ENSG00000136694.
Subcellular location: Cytoplasm; Secreted
Pathways (Reactome):
Immune System: Interleukin-36 pathway
Gene Ontology:
Molecular function: protein binding; cytokine activity; interleukin-1 receptor binding
Biological process: cellular response to lipopolysaccharide; cytokine-mediated signaling pathway; immune response; inflammatory response
Cellular component: cytoplasm; extracellular region
Genetic constraint (gnomAD): Loss-of-function variants: 8 observed, 10.55 expected, observed/expected ratio (o/e) 0.76, 90% interval 0.44 to 1.36. The upper end of that interval is the gene's LOEUF score, 1.36, which puts it in group 5 of 6, group 1 being the genes least tolerant of losing a copy. Missense variants: 191 observed, 198.1 expected, observed/expected ratio (o/e) 0.96, 90% interval 0.86 to 1.09. Synonymous variants: 71 observed, 75.25 expected, observed/expected ratio (o/e) 0.94, 90% interval 0.78 to 1.15.
Homologues: Orthologues: chimpanzee IL36A (99% identical), macaque IL36A (91% identical), rabbit IL36A (64% identical), rat Il36a (56% identical), mouse Il36a (54% identical), zebrafish il1fma (24% identical), zebrafish il1b (23% identical). Paralogues in human: IL36G (56% identical), IL36B (45% identical), IL37 (32% identical), IL36RN (29% identical), IL1RN (28% identical), IL1B (27% identical), IL1F10 (25% identical).
Diseases named in the same sentence as IL36A in open-access papers:
IL36A is named in the same sentence as 27 diseases in open-access papers, as found by Europe PMC text mining. Sharing a sentence is not in itself a finding about the gene and the disease. The quoted sentences say what the papers report.
psoriasis (18 papers, 2013 to 2025). An autoimmune condition characterized by red, well-delineated plaques with silvery scales that are usually on the extensor surfaces and scalp. "Top up-regulated DEGs in CP vs C include previously identified psoriasis-associated genes such as IL36A/G, SPRR2A/B/F, SERPINB4, S100A7A, S100A9, and IL17F while top down-regulated DEGs include SERTM1, IL6, and ADAMTS16." (PMID 30054515, 2018). "Molecular analysis of the skin of IgG- and anti-IL36R-treated K14-IL17Aind mice revealed effective suppression of psoriasis-associated cytokines (Il36a, Il36g, Il36b, Il23a, and Tnf), chemokines (Cxcl1, Cxcl5, and Ccl2) and antimicrobial-peptides (such as Defb4) on mRNA level." (PMID 38162658, 2023). "Il36a was required for the development of IMQ-induced murine psoriasis, whereas deletion of Il36a resulted in significant improvement in the skin lesions; however, deficiency of Il36b or Il36g had no impact on reducing disease severity." (PMID 38077370, 2023). "Psoriasis expressed preferential Th17 skewing, with a significant increase in Th17-related factors (IL-17A/F and IL-36A/G)." (PMID 36465933, 2022). "mRNA from other proinflammatory cytokines associated with psoriasis pathogenesis, IFNG, TNFA and IL-1 family members IL1B and IL36A were also markedly elevated in psoriatic lesional skin." (PMID 28790368, 2017). "Especially IL-36A was noted, as recent studies have found that IL-36 cytokines, that belong to IL-1 family, have significant role in regulation of psoriasis and psoriasis activity." (PMID 26176783, 2015). "IL1F6 (IL36A) is a gene that was recently found to be part of the signalling system what is active in psoriasis." (PMID 25897967, 2015). "Furthermore, the transcriptional signature from affected skin revealed upregulation of key human psoriasis genes, including Lcn2 and Defb4, cytokines Tnf, Il1b, and Il36a/g, and chemokine ligands Ccl2, Cxcl9, and Ccl20." (PMID 38528069, 2024). "Furthermore, mice with forced overexpression of IL-36a in the skin was created, and a similar skin inflammatory condition existed in human psoriasis." (PMID 34675805, 2021). "Furthermore, successful treatment of psoriasis with the anti-psoriatic standard treatment etanercept is accompanied by a decrease in IL36A, IL36G and IL36RN expression." (PMID 32484435, 2020). "In our study we only found IL36 cytokines (IL36G, IL36RN and IL36A) to be related to psoriasis." (PMID 25897967, 2015). "IL36G was also highly expressed in psoriasis, and correlation analysis indicated that IL36G was closely related to IL36A, IL19, CXCL1, and CXCL8, all of which participate in the pathogenesis of psoriasis." (PMID 40159643, 2025). "Most well known psoriasis related genes activated in non-lesional skin are IL6, IL22, IL36A, IL36G, IL19, IL20, S100A7 and S100A12." (PMID 25897967, 2015).
lupus nephritis (2 papers, 2013 to 2017). Glomerulonephritis in the context of systemic lupus erythematosus. "IL-1 family member 6 (IL-1F6, also known as IL-36α) is overexpressed in injured DTs from various mouse kidney diseases, including lupus nephritis, diabetic nephropathy, and traumatic kidney injury." (PMID 29109726, 2017).
atopic dermatitis (1 paper, 2021). "The reported list of inflammatory mediators found in atopic dermatitis includes S100A7, S100A8 S100A9, CCL2, CCL3, IL36A, IL36G, and IL36RN." (PMID 34925353, 2021).
autoimmune disease (1 paper, 2025). A disorder resulting from loss of function or tissue destruction of an organ or multiple organs, arising from humoral or cellular immune responses of the individual to their own tissue constituents. "IL36A and IL21 actively participate in autoimmune disease, activating downstream pro-inflammatory pathways, thus promoting inflammatory responses." (PMID 39762453, 2025).
COVID-19 (1 paper, 2021). A disease caused by infection with severe acute respiratory syndrome coronavirus 2. "Evidence of inflammatory cytokine signaling by IL17 and IL36A was predicted in COVID-19 lung and airway compartments." (PMID 33782412, 2021).
Crohn disease (1 paper, 2024). A gastrointestinal disorder characterized by chronic inflammation involving all layers of the intestinal wall, noncaseating granulomas affecting the intestinal wall and regional lymph nodes, and transmural fibrosis. "Other notable markers up-regulated selectively in CD submucosa/wall compared to control include IL36a, IL16, and complement C9, while C6 is selectively increased in mucosa, highlighting a potential and perhaps underappreciated role for complement in the pathogenesis of Crohn’s disease." (PMID 38791146, 2024).
generalized pustular psoriasis (1 paper, 2017). A rare and extreme form of psoriasis characterized by the appearance of sterile pustules which can take many patterns. "Indeed, the S100A cluster was most closely co-regulated with IL36A whose excessive activity is involved in monogenic generalized pustular psoriasis, which is histologically characterized by the predominance of neutrophil infiltrations in the case of mutation in its antagonist IL36RN35–37." (PMID 28790368, 2017).
influenza (1 paper, 2020). An acute viral infection of the respiratory tract, occurring in isolated cases, in epidemics, or in pandemics; it is caused by serologically different strains of viruses (influenzaviruses) designated A, B, and C, has a 3-day incubation period, and usually lasts for 3 to 10 days. "Further analysis revealed that elevated level of IL-36G and IL-36A were statistically correlated with COX-2 in the influenza patients (IL-36G: R = 0.68, P = 0.0018; IL-36A: R = 0.82, P < 0.0001)." (PMID 33193319, 2020).
non-small cell lung carcinoma (1 paper, 2025). A group of at least three distinct histological types of lung cancer, including non-small cell squamous cell carcinoma, adenocarcinoma, and large cell carcinoma. "Studies have shown that IL-36A is an important predictor of unfavorable prognosis in patients with non-small cell lung cancer." (PMID 40606972, 2025).
osteoarthritis (1 paper, 2018). A noninflammatory degenerative joint disease occurring chiefly in older persons, characterized by degeneration of the articular cartilage, hypertrophy of bone at the margins and changes in the synovial membrane. "It was also recently shown that IL-36A is elevated in synovial tissues of patients with psoriatic and rheumatoid arthritis (compared with osteoarthritis), suggesting a possible role for IL-36 in the development of psoriatic arthritis (PsA) as well." (PMID 29434599, 2018). "In agreement with this, IL-36A and IL-36B abundance were significantly elevated in serum of rheumatoid arthritis patients compared with healthy CTLs, and IL-36A was also elevated in synovial tissues from rheumatoid arthritis patients as compared with osteoarthritis patients." (PMID 29434599, 2018).
Pruritus (1 paper, 2023). Pruritus is an itch or a sensation that makes a person want to scratch. "It was shown that the expression of genes encoding inflammatory mediators such as CCL4, CCL7, CCL8, CCL20, interleukin-19 (IL-19), IL-20, IL-26, IL-36A, IL-36G, and TNF-α) was unique to psoriatic skin with pruritus." (PMID 37834183, 2023).
psoriasis vulgaris (1 paper, 2023). Plaque psoriasis is the most common presentation of psoriasis. "IL-36 receptor expression (encoded by IL1RL2), as well as the expression of IL36A, IL36B, and IL36G are significantly upregulated in psoriasis vulgaris skin lesions, compared to healthy and non-lesional skin samples." (PMID 38162658, 2023).
Sjögren's syndrome (1 paper, 2017). "Serum levels of IL-36a were correlated with disease activity, indicating a possible function of this cytokine in controlling the activation of the immune network in Sjögren's syndrome." (PMID 28611508, 2017).
vitiligo (1 paper, 2018). Generalized well circumscribed patches of leukoderma that are generally distributed over symmetric body locations and is due to autoimmune destruction of melanocytes. "Like multiple previous studies we could only detect very moderate upregulation of some inflammatory cytokines such as TNF (p < 0.05) and IL36A (alias IL1F6) (p < 0.05) in vitiligo lesional or non-lesional skin." (PMID 30515176, 2018).
tumor (4 papers, 2019 to 2025). "Earlier research has indicated that IL-36A could be closely linked to the tumor immune microenvironment." (PMID 40606972, 2025). "The function of IL-36A in the tumor microenvironment is also receiving increasing attention, with one of the main mechanisms being the enhancement of immune cell infiltration through upregulation of the expression of various chemokines." (PMID 40606972, 2025). "The cytokines of the first group include L1A, IL36A and CCL13, which, as immune stimulatory mediators, may contribute to an anti-tumor immune response and thus a favorable clinical outcome." (PMID 31588238, 2019).
IL36A also shares sentences with these, for which no sentence is quoted: cancer (2 papers); Hyperkeratosis (2); acne inversa (1); acute kidney injury (1); atherosclerosis (1); cardiac hypertrophy (1); cardiovascular disease (1); inflammation (1); kidney diseases (1); lung carcinoma (1); nephritis (1); rheumatoid arthritis (1).